GATA3 (GATA binding protein 3)
Diseases named in the same sentence as GATA3 in open-access papers (continued):
Sharing a sentence is not in itself a finding about the gene and the disease.
tumor (continued). "Additionally, the reliance on GATA3 expression alone may not provide a complete picture of the tumor’s behavior and prognosis." (PMID 39768217, 2024). "Because p18−/− luminal tumor cells did not generate tumors when they were transplanted into MFPs without exogenous estrogen, we were unable to determine and compare the effect of estrogen in inducing DNA damage in p18−/− (Gata3+/+;Brca1+/+) luminal type tumorigenesis." (PMID 38627785, 2024). "Therefore, we sought to determine whether GATA-3 is a bona fide proto-oncogene and to further characterize GATA-3 dependent transcriptional programs across the spectrum of immature and mature T-cell derived neoplasms." (PMID 36329027, 2022). "However, H1299 cell knockdown GATA3 combined with 20 Gy irradiation did not reduce the tumor." (PMID 35993027, 2022). "Notably, correlation analysis revealed a significant correlation between expression levels of ESR1 and GATA3 in non-cancerous tissues despite lack of correlation in tumor tissues, suggesting the impact of cancer development on the functional association between these two genes." (PMID 34094972, 2021). "Immunohistochemical results: Tumor cells are diffusely positive for P40, P63, CK7, and P16, while negative for GATA3, CK20, and HPV." (PMID 41239619, 2025). "In contrast, the majority of tumours in the GATA3–LOFDEL group belong to the luminal molecular subtype (56.3% for luminal-A and 40.2% for luminal-B), while only 3.4% of tumours are HER2-enriched, and no basal-like tumours." (PMID 40585280, 2025). "In ER‐negative EPC‐like tumours with high nuclear grade, high mitotic activity, and no peripheral MEC layer, it is helpful to perform GATA3 and SOX10 IHC to support primary breast origin as metastatic tumours with papillary morphology should be excluded." (PMID 39209705, 2025). "The tumor cells exhibited positivity for CK7 (partial), CK20, CDX2, and CAM5.2, while being negative for GCDFP15, S100, SOX10, GATA3, PAX8, and CK5/6." (PMID 40438862, 2025). "Conversely, progesterone receptor (PR) was negative in the only tested case, as well as GATA-3, SALL-4, PTEN, PAX-2, AFP and calretinin, while ARID1A was retained in one case and another tumor has a CK7+/CK20− phenotype." (PMID 39996865, 2025). "GATA3 and IFN-γ expressions were significantly higher in tumor tissue of the responders compared to non-responders." (PMID 40736702, 2025). "The tumor was histologically composed of oncocytic cells that expressed KRT7, vimentin, SDHA, SDHB and fumarate hydratase, but not KIT, GATA3 and alpha-methylacyl-CoA racemase." (PMID 39980061, 2025). "Tumor cells typically show diffuse strong positivity for P40, P63, CK5/6, and CK7, while GATA3, Villin, and CK20 are negative." (PMID 41239619, 2025). "Immunohistochemical analysis of the tumor specimen demonstrated that the tumor was PAX8 positive and GATA3 negative, consistent with the pathological findings of the current case." (PMID 40979509, 2025). "An immunohistochemical study was performed, showing positive staining of the tumor cells for inhibin and calretinin and absence of staining for GATA-binding protein 3 (GATA3)." (PMID 41035579, 2025). "Immunohistochemical staining showed that the tumor cells were positive for CKAE1/AE3, CK8/18, CK7, 34βE12, and GATA-3, while negative for p63, Vimentin, MUC5AC, MUC6, Hep-1, AFP, CK20, CDX2, MUC2, CD10, CK5/6, CD56, Syn, and CgA." (PMID 40917856, 2025). "Specifically, gene expression did not vary significantly with gender (SOX9: p = 0.25; GATA3: p = 0.69; GATA4: p = 0.45), age group (<60 vs. ≥60 years; p range = 0.29–0.87), or tumor site (trunk vs. extremities; p range = 0.38–0.90)." (PMID 41303462, 2025).
tumor (continued). "However, both groups with GATA3 inactivation, whether by methylation, LOF mutations or deleterious CNA, are associated with a worse relapse prognosis compared to tumours in which GATA3 is expressed and not mutated, regardless of the specific inactivation mechanism." (PMID 40585280, 2025). "The tumours are positive for AMACR, CK7, Vimentin, and CD10 and need to be differentiated from papillary neoplasm with reverse polarity which are GATA3 positive, vimentin negative, and AMACR positive." (PMID 38265103, 2024). "These included positive readings for ER (95%), PR (5%), cytokeratin-7 (CK-7), and GATA binding protein 3 (GATA-3), while P63 and KIT (CD117) were absent in the tumor cells and HER-2/neu score was zero." (PMID 39125514, 2024). "The tumor was positive for AMACR, negative for GATA3, and rarely/focally positive or completely negative for CK7 and CAIX." (PMID 39703302, 2024). "By IHC, the tumor cells showed patchy positive staining for AE1/AE3, while they were negative for GATA3." (PMID 40093349, 2024). "On immunohistochemistry, the tumor cells were positive for S100P and SOX-10 and focally positive for HMB-45 and Melan A. Tumor cells were negative for CK, EMA, SMA, TTF1, PAX8, GATA3 and SALL4." (PMID 38509523, 2024). "Of note, GATA3 and KRT14 were not considered in this study, as they were present in either most or almost no tumor samples, respectively." (PMID 39337385, 2024). "In the spectrum of renal epithelial tumors, GATA3 is usually expressed by PRNRP and CCPRCT, while being consistently negative in other tumor types." (PMID 38791935, 2024). "The invasive carcinoma, IC, and tumor cells involved in PS expressed PSA and P504S, while CK7, CK20, CDX-2, and GATA-3 were negative." (PMID 37374005, 2023). "Immunophenotypically, tumor cells usually express EMA, CK7, GATA3, and L1CAM, while CD117 and CAIX are negative." (PMID 37924117, 2023). "Immunohistochemistry staining showed the tumour was positive for AE1/3, CK7, GATA-3 and GCDFP-15; and was negative for CK20, PAX-8, CDX-2, WT-1, TTF-1, mammaglobin and BRAF V600E." (PMID 36871042, 2023). "In our case, the tumor cells displayed uniform staining for PSA and PSAP, and they were negative for GATA-3, CDX-2, CK7, and CK20." (PMID 37374005, 2023). "As per immunohistochemistry, the tumor cells were diffusely positive for SF-1 and Ki-67, partially positive for inhibin, and negative for CAM5.2, CK7, CK20, C-KIT, CD30, LCA, GATA-3, TTF-1, and PAX8." (PMID 36335378, 2022). "Immunohistochemical stains showed the tumor cells to be positive for CDX2, CK20, and SATB2 and negative for p63, GATA3, CK7, and Uroplakin II, indicating the colorectal origin of the tumor." (PMID 35178262, 2022). "The tumor cells strongly expressed CK7 and GATA3, and a dual-labeling showed negative PHH3 labeling for the melanocytes." (PMID 35386919, 2022). "In one tumor (case 4) with focal PAX2 expression, similar to GATA3, there was no significant morphological difference between PAX2-positive and PAX2-negative areas." (PMID 35204416, 2022). "At the same time, immunohistochemistry in tumor 2 showed that these malignant cells were positive for ER and GATA binding protein 3 (GATA-3) but negative for epidermal growth factor receptor (EGFR) and cytokeratin 5/6 (CK5/6)." (PMID 36578949, 2022). "In this study, for all cases tested, the tumor cells are positive for PAX8, GATA3, TTF1, and luminal CD10, and are negative for ER and PR, consistent with the immunohistochemical results previously reported." (PMID 35865471, 2022).
tumor (continued). "Furthermore, according to the Venn diagram, 75 genes in the entire patient group and 46 in ER-positive subgroup, were differentially expressed between GATA3-mutant and non-mutant tumors that may indicate the impact of GATA3 in the expression profile of the tumor cells." (PMID 33462316, 2021). "Reportage of tumor RORC-Treg infiltration was calculated from the averaged, normalized levels of FOXP3, CTLA4, GITR, RORC and GATA3." (PMID 34681642, 2021). "The results indicated that the expression of GATA1, GATA4 and GATA6 remarkably varied across the tumor stages, whereas GATA2, GATA3 and GATA5 demonstrated no significantly changes in different tumor stages." (PMID 34093794, 2021). "Tumor samples with absent immunoexpression of GATA3, FOXA1 and CK5/6 showed significantly lower transcript levels of GATA3, FOXA1 and KRT5/KRT6A, respectively (p < 0.001, p = 0.0130, p < 0.0001 and p = 0.0278)." (PMID 32758253, 2020). "Additionally, expression of GATA binding protein 3 (GATA3), which encodes a trans-acting T-cell specific transcription factor protein, was significantly decreased in the MYB-NFIB fusion sample (RPKM was 601 in fusion sample, 13072 on average in no-fusion tumor samples)." (PMID 29299133, 2017). "On the contrary, tumours with significantly increased TUG1 expression, which encompass 8% of TCGA cases, were usually positive for markers of a luminal subtype, e.g. FOXA1, GATA3, but not for basal KRTs." (PMID 28430799, 2017). "By immunohistochemistry, the tumor showed a triple-negative breast cancer (TNBC) phenotype (ER−/PR−/HER2-), negative for E-cadherin, positive for GATA-3, and the Ki-67 index was approximately 40%." (PMID 28693516, 2017). "One portion of the SCCL/Mes‐Inf cluster was negative for KRT5/KRT14 and FOXA1/GATA3, as well as for CDH3 expression, making it distinct from basal/SCC‐like tumours." (PMID 28195647, 2017). "In the analysis stratified by tumor size, the DFS curves were not statistically different between GATA3-positive and -negative cases among cases with ≤ 5-cm tumors (P = 0.1586)." (PMID 27249072, 2016). "Comparison of GATA3 and GATA5 methylation in matched tumor (TU) and adjacent normal (adN) tissues demonstrated tumor-specific hypermethylation." (PMID 24549248, 2014). "Basal-like subtype tumours were negative for FOXA1 (B3) and for GATA-3 (B4) in 85.7% and 84.6% of the cases, respectively." (PMID 19549328, 2009). "However, correlation analyses revealed that D2 expression varied independently from GATA3 and UPK3A across both tumor and non-tumor groups." (PMID 41585944, 2026). "Immunohistochemical analysis disclosed positive staining to AE1/AE3, CK20, CK5/6, P40, c-kit and NCAM, and negative staining to CK-7, CK-8, AFP, GATA3, PSA, synaptophysin, and chromogranin A. Thus, the tumor of epithelial cell origin was confirmed through AE1/AE3 positive staining." (PMID 41515615, 2026). "Immunohistochemically, the tumor cells were diffusely positive for CAM5.2, AE1/AE3, and ER; focally positive for CD10, EMA, vimentin, WT1, CDX2, and p16; and negative for PAX8, CK7, calretinin, GATA3, Napsin A, and TTF1." (PMID 40959354, 2025). "Original tumor tissue of p-UC was characterized immunohistochemically for luminal urothelial differentiation by negative KRT5/6 staining (Fig. 3Aii) and strong GATA3 staining (Fig. 3Aiii)." (PMID 40251219, 2025). "If CDX2 and SATB2 are both negative, or if CK7 is positive but CK20 and TRPS1 are negative, third-tier immunostains including p63, GATA3, uroplakin II/III, PSA, and NKX3.1 should be performed to further classify the tumor as urothelial or prostatic secondary EMPD." (PMID 41463263, 2025). "Immunohistochemical analysis revealed the following results: Tumor cells were negative for Ckp, positive for desmin and actin, negative for myogenin, positive for MyoD1, and negative for CgA, S-100, Syn, h-caldesmon, SMA, Sox-10, Pax-8, and GATA3." (PMID 39139286, 2024).
tumor (continued). "However, the tumor cells were negative for CD3, highlighting T cells in the background, and were negative for CK (AE1/AE3) and GATA3, highlighting the trapped ductal epithelium of the breast." (PMID 37884941, 2023). "Similar to what was observed in Braf/Pten tumor-draining ILNs, MC903 treatment–promoted GATA3+ Tregs in Braf ELNs exhibited signature expression of ST2, OX40, and PD-1, but not IL-4 and IL-13 which were only detected in GATA3+ Th2 cells." (PMID 36107619, 2022). "Immunohistochemistry showed that the tumor cells were diffusely positive for SF-1 and Ki-67, partially positive for inhibin, and negative for CAM5.2, CK7, CK20, C-KIT, CD30, LCA, GATA-3, TTF-1, and PAX8." (PMID 36335378, 2022). "In the current study, all PRNRP cases exhibited a diffuse and strong expression of PAX8, CK7, and GATA3, whereas the expression of AMACR, CD10, and vimentin was either absent or only weak and focal, and the tumor cells were completely negative for CD117 and CAIX." (PMID 35936734, 2022). "Most tumor cells of the neuroendocrine component were immunoreactive for CAM.5.2, cytokeratin (CK) 7, CK AE1/AE3, synaptophysin, chromogranin A, parathormone, GATA3, and parafibromin, whilst they were negative for thyroglobulin, TTF1, calcitonin, glucagon, and S100." (PMID 32506375, 2021). "However, these two basal/SCC‐like tumour categories do not differ in their KRT5, KRT14/FOXA1, GATA3 ratios, their defining characteristics, or their shifts to high CDH3 and lower CDH1 expression." (PMID 28195647, 2017). "When visualized using RNA in situ hybridization, this transcript showed elevated expression in early neoplasia and cancer compared with normal, with staining patterns correlating well with the elevated staining of ER, FOXA1, and GATA3 in the majority of neoplasia cases (data not shown)." (PMID 24887547, 2014). "In summary, we report 2 cases of a high-grade tumor diagnosed as non-ITAC of the sinonasal region, characterized by overt hypercellularity, largely solid growth pattern with comedo-like necrosis, immunohistochemical positivity for p40/p63, S100, SOX10, and GATA3, with a recurrent ETV6::NTRK3 fusion." (PMID 37415052, 2023). "In addition to the antigens described here, the original tumor was positive for CKC, CK7 and CK 5/6, negative for GATA3, CDX2, ERα, CK20,p63, AFP, CA19.9, TTF1 and PAX 8 and with patchy/focal staining for calretinin, CD10, RCC, BerEP4 and WT‐1 (data not shown)." (PMID 30109783, 2018). "Similarly, further studies are needed to determine the frequency of ER+ tumors that are negative for both PR and CAXII (one tumor in our cohort, positive for FOXA1 and GATA3), and whether these tumors are also negative for other ER target genes and are unresponsive to hormonal therapies." (PMID 36358871, 2022).
cancer (353 papers, 2008 to 2026). A tumor composed of atypical neoplastic, often pleomorphic cells that invade other tissues. "Other known mechanism for up-regulation of GATA3 expression include transcriptional activation by cancer-associated pathways as the NOTCH1 and NFkB pathway as well as GATA3 promoter hypomethylations." (PMID 39979991, 2025). "Within pT2–pT4 carcinomas, high AR immunostaining was associated with GATA3 (p < 0.0001) and CK20 (p < 0.0001) positivity, p63 expression loss (p = 0.0013), and low PD-L1 expression in cancer cells (p < 0.0001)." (PMID 41463239, 2025). "An association between GATA3 expression and cancer aggressiveness has also been previously reported." (PMID 38668712, 2024). "Taken together, these data indicate that reconstitution of Gata3 in Brca1-deficient cancer cells restores the efficiency of DNA damage repair and suppresses mesenchymal differentiation in inhibition of tumorigenesis." (PMID 38627785, 2024). "Breast, urothelial, and BCC cancers have the highest GATA3 expression; the limited expression of GATA3 in specific tissues has made it useful as a diagnostic IHC marker in cancers in these tissues." (PMID 38668712, 2024). "Loss of GATA3 expression leads to the dedifferentiation of luminal epithelial cells, leading to cancer progression and metastasis." (PMID 37454130, 2023). "Corynebacterium, Prevotella, and Peptostreptococcus were positively associated with GATA3 expression in cancer, while its expression in precancer samples was associated with distinct and several bacteria." (PMID 37409975, 2023). "These clinical findings, consistent with our results in mice, further confirm that loss of GATA3 promotes basal-like cancer development and progression." (PMID 34976209, 2022). "This was because the SATB1-gene interaction network generated by FunRich software suggested that SATB1 was closely associated with other cancer-correlated genes, such as GATA3, HDAC1, and MTA2." (PMID 34604093, 2021). "Nine key pathways, which were associated with 11 cancer hallmarks, were affected in the cancer spots with GATA3 mutations compared with the findings in the mutation-negative spots." (PMID 33795819, 2021). "Among a total of 422 spots representing pathologically identified cancer cells, GATA3 mutation reads were detected in 46 spots by analyzing Visium reads." (PMID 33795819, 2021). "The rest of GATA3 were associated with either survival advantage or disadvantage depending on the cancer types." (PMID 34301206, 2021). "Our RNA-seq analysis validated the known mutations in cancer-related genes, GATA3 and CDKN2A, that have been reported for the three commercial CLs." (PMID 35011679, 2021). "The largest such coefficient in the gene-wide GATA3 task trained on METABRIC-(LumA) belonged to MEGF10, which has been previously implicated in cancer processes downstream of GATA3." (PMID 33957863, 2021). "It is expressed more frequently than ER and PR, but like GATA3, its expression is closely linked to ER expression, with a positivity between 25% and 35% in TN carcinomas." (PMID 34771579, 2021). "Favorable prognosis was observed in patients presenting high expression of “luminal like” genes (AR, GATA3) and decreased survival was observed in patients expressing cancer stem cell-like (WNT11) or EMT-associated genes (MMP28)." (PMID 32708049, 2020). "In cancer, nuclear loss of GATA3 is associated with the progression to castration-resistant prostate cancer (CRPC) and poor prognosis." (PMID 32894216, 2020). "Based on the functional screening of 90 cancer-associated transcription factors, we found that GATA3 is a positive regulation of APOBEC3B gene expression." (PMID 32934779, 2020).